RNU6-8 (RNA, U6 small nuclear 8)
Synonyms: U6-8; RP105
Gene: Small nuclear RNA gene on chromosome 14 (32,203,163 to 32,203,269, reverse strand). Ensembl gene ENSG00000202337.
Gene Ontology:
Molecular function: U4 snRNA binding
Biological process: formation of quadruple SL/U4/U5/U6 snRNP; spliceosomal tri-snRNP complex assembly
Cellular component: U4/U6 x U5 tri-snRNP complex; U6 snRNP
Homologues: Orthologues: guinea pig U6 (100% identical), mouse Gm23296 (100% identical), mouse Gm24859 (100% identical), pig U6 (100% identical), rabbit U6 (100% identical), rat U6 (100% identical), chimpanzee U6 (98% identical). Paralogues in human: RNU6-7 (100% identical), RNU6-1 (99% identical), RNU6-2 (99% identical), RNU6-3P (99% identical), RNU6-4P (99% identical), RNU6-5P (99% identical), RNU6-6P (99% identical), RNU6-9 (99% identical), RNU6-11P (98% identical), RNU6-12P (98% identical), RNU6-13P (98% identical), RNU6-17P (98% identical), and 1288 more.